MIR329-1 (microRNA 329-1)
Synonyms: hsa-mir-329-1; MIRN329-1; mir-329-1
Gene: MicroRNA gene on chromosome 14 (101,026,785 to 101,026,864, forward strand). Ensembl gene ENSG00000207761.
Gene Ontology:
Biological process: miRNA-mediated post-transcriptional gene silencing
Cellular component: RISC complex
Homologues: Orthologues: chimpanzee ptr-mir-329-1 (100% identical).